TLR9 (toll like receptor 9)
Diseases named in the same sentence as TLR9 in open-access papers (continued):
Sharing a sentence is not in itself a finding about the gene and the disease.
glioma (39 papers, 2010 to 2025). A benign or malignant brain and spinal cord tumor that arises from glial cells (astrocytes, oligodendrocytes, ependymal cells). "The underlying molecular mechanisms behind TLR9 signaling activation are also needed to better understand the process of these dual effects of TLR9 in gliomas." (PMID 36611945, 2022). "The aim of this study was to evaluate the expression of TLR9 in a large series of glioma samples with tissue array and to examine the association between TLR9 expression, clinicopathological variables, and patient outcome." (PMID 20696081, 2010). "Several studies indicate that TLR9 expression in gliomas has been associated with malignancy." (PMID 41157253, 2025). "Increased expression of TLR9 was associated with higher glioma grade and worse prognosis." (PMID 34715891, 2021). "CXCR-4 may thus underlie the mechanism for TLR9 enhancement of the metastatic potential of glioma cells." (PMID 25411122, 2014). "In addition, CCL2/CCL5, MMP-2, and MMP-9 have been implicated in TLR9-mediated glioma progression." (PMID 34715891, 2021). "By decorating the nanodiscs with CpG oligonucleotides, and establishing TLR9 agonists, we aimed to stimulate the immune system further and enable immunological memory against glioma in the case of recurrence." (PMID 40249282, 2025). "Using a murine glioma model, we investigated a modified DC vaccine strategy involving the synergistic ex vivo activation of TLR9 and TLR3 with CpG ODN and poly(I:C), respectively." (PMID 41294838, 2025). "Huang's study demonstrated that dual stimulation of TLR3/TLR9 pathways in myeloid cells of the microglia/macrophage lineage enhances glioma suppression efficacy." (PMID 40838069, 2025). "Synthetic high‐density lipoprotein (sHDL) nanodiscs are developed to co‐deliver liver‐X‐Receptor (LXR) agonists and Toll‐like receptor 9 (TLR‐9) agonist CpG for glioma treatment." (PMID 40249282, 2025). "SWNT/CpG also explicitly reduces the NF-β activation in glioma cells while triggering macrophages by inducing the Toll-like receptor 9 (TLR9)/NF-β pathway." (PMID 38686045, 2024). "While findings point to TLR9 as a potential target in glioma immunotherapy, CpG-ODN treatment in a rat glioma model was shown to increase the size of the tumor after intratumoral injection." (PMID 38893093, 2024). "Based on the information presented by the investigators, TLR9 is an important molecule that can induce or stimulate immune responses against gliomas." (PMID 36611945, 2022). "This article reviews the roles of TLR9 in the pathogenesis of glioma and its related signaling molecules in either defending or promoting glioma." (PMID 36611945, 2022). "Synergistic activation of TLR3 and TLR9 in microglia reinforces the secretion of pro-inflammatory factors, phagocytic activity, and suppression of glioma growth." (PMID 36611945, 2022). "The TLR9 agonist CpG ODN 107 also enhances the radiosensitivity of human glioma U87 cells by blocking tumor angiogenesis." (PMID 36611945, 2022). "Further studies are needed to clarify the dual functions of TLR9 in glioma development and progression." (PMID 36611945, 2022). "TLR9 was reported to be expressed in human glioma cell lines U251 and U87, the murine cell line C6 primary human glioma biopsies, and isolated GSCs." (PMID 36611945, 2022). "Although TLR9 is involved in the immune response against glioma to eliminate the tumor, its pro-tumoral role in glioma development has been investigated in several studies." (PMID 36611945, 2022). "Synergistic TLR-3/TLR-9 activation in microglia/macrophages suppressed glioma growth mediated by interferon β release and phagocytic tumor clearance." (PMID 34439380, 2021). "On the other hand, it is also considered as a potential radiosensitizer to enhance the response of glioma cells to radiotherapy via TLR9 signaling." (PMID 34715891, 2021).
glioma (continued). "TLR9 was reported to express on human glioma cell line U251, U87, primary human glioma biopsies, and isolated human glioma stem cells (GSCs)." (PMID 34715891, 2021). "Activation of TLR3, TLR4, and TLR9 has been reported to reinforce the antitumor response to anti-PD-1/PD-L1 and exhibit immune checkpoint delayed resistance in glioma cells or animal models." (PMID 34715891, 2021). "Immune responses to CpG are mediated by Toll-Like Receptor 9 (TLR9), which is located primarily on antigen presenting cells, including dendritic cells and CNS microglia, as well as glioma cells." (PMID 34277419, 2021). "Up to date, TLR2, TLR3, TLR4, TLR7, and TLR9 have been intensely studied in glioma, while less or missing information is available regarding the mechanisms of TLR1/TLR6 (dimerizes with TLR2), TLR5, TLR8 (dimerizes with TLR7), and particularly TLR10." (PMID 34715891, 2021). "Western blotting showed that the level of MYD88 decreased in primary glioma cells after siRNA targeting TLR9." (PMID 32843056, 2020). "Stimulation of TLR9 with ODN 1826 induces caspase-3-dependent apoptosis in gliomas and prolongs the survival of C57BL/6 mice with an intracranially implanted glioma cell line (GL261)." (PMID 31240216, 2019). "IGF-1 also regulates inflammatory responses in glioma cells via influencing hypoxia-inducible factor (HIF)-1α-toll-like receptor 9 (TLR9) cross talk." (PMID 31805126, 2019). "TLR9 is overexpressed in glioma stem cells, and a correlation between the expression level of TLR9 and survival rate in glioblastoma has been reported." (PMID 30109213, 2018). "The mechanism underlying the radiosensitizing effect of CpG ODN107 was closely related to autophagy, with the TLR9-ERK-mTOR signaling pathway being critical for the induction of autophagic cell death in glioma cells." (PMID 27251306, 2016). "Further, the TLR9-ERK-mTOR signaling pathway was critical for this type of autophagic cell death induced by CpG ODN107+ irradiation in glioma cells." (PMID 27251306, 2016). "In the case of TLR4 and TLR9 agonists, the recommendation is to remain cautious when considering their roles in anti-glioma therapies." (PMID 25411122, 2014). "Activated TLR9 also promoted growth of glioma stem-like cells through the activation of STAT3 signaling in vitro, which is a pathway participating in numerous tumor promoting activities." (PMID 25411122, 2014). "TLR2, TLR4, and TLR9 have been under investigation for expression on glioma cells, and their contribution to tumor development has been mostly described as tumor promoting." (PMID 25411122, 2014). "These nanoparticles can be used to enhance the uptake of CpG oligonucleotides, an agonist of toll-like receptor 9 (TLR-9), by glioma-associated inflammatory cells." (PMID 23864876, 2013). "Our data indicated that TLR9 is expressed in glioma cell lines and glioma tissues, and the expression of TLR9 in glioma cells is functional." (PMID 20696081, 2010). "Our data indicated that TLR9 expression increases according to the histopathological grade of glioma, and the TLR9 expression level is related to the PFS of GBM patients." (PMID 20696081, 2010). "Chloroquine significantly inhibited CpG ODN induced invasion in glioma cells, which suggest that TLR9 signaling is responsible for the enhanced invasion of U87 cells induced by CpG ODN." (PMID 20696081, 2010). "All the results suggested that the expression of TLR9 in glioma cells is functional and related to the invasiveness of glioma cells." (PMID 20696081, 2010). "Present data indicated that TLR9 expression increases according to the histopathological grade of glioma, and the TLR9 expression level is related to the PFS of GBM patients." (PMID 20696081, 2010). "The expression of TLR9 mRNAs in glioma cell lines and tumor tissues were examined using RT-PCR method." (PMID 20696081, 2010). "The tissue array analysis indicated that TLR9 expression is correlated with malignancy of glioma (p < 0.01)." (PMID 20696081, 2010).
glioma (continued). "CpG ODN can significantly enhance the invasion of GBM cells, we confirmed that TLR9 signaling was responsible for the enhanced invasion of glioma cells induced by CpG ODN." (PMID 20696081, 2010). "The expression of TLR9 in glioma tissues is a major factor, through them, glioma cells can recognize either microbial pathogens or cellular debris and promote the expression and secretion of chemokines and cytokines." (PMID 20696081, 2010). "Screening a large collection of human glioma samples in tissue array with immunohistochemistry, we found that TLR9 expression correlated to the malignancy of gliomas, and TLR9 expression is an independent prognostic factor to predict patient PFS in GBM." (PMID 20696081, 2010). "We screened the expression of TLR9 in a large collection of human glioma samples in tissue array with immunochemistry." (PMID 20696081, 2010). "We next analyzed the correlation between the expression of TLR9 protein and the histological staging of gliomas." (PMID 20696081, 2010). "RT-PCR and immunofluorescence were used to determine the expression of TLR9 in glioma cell lines and clinical glioma samples." (PMID 20696081, 2010). "TLR9 expression was detected in all high grade glioma cases and was highly expressed(score >4) in 43.78% (88/201) cases." (PMID 20696081, 2010). "To study the effects of TLR9 stimulation on the invasion behavior of glioma cells, we performed invasion assays using the well characterized TLR9 agonist, ODN2006." (PMID 20696081, 2010). "Moreover, TLR2, TLR3, TLR4, TLR7, TLR8, and TLR9 have emerged as critical modulators of glioma biology." (PMID 41157253, 2025). "Members of our research group have previously reported that combined activation of TLR3 and TLR9 may enhance the antitumor function of microglia through a synergistic effect, thereby offering a new strategy for glioma immunotherapy." (PMID 41294838, 2025). "Glioma stem cells express high levels of TLR9, leading to STAT3 activation." (PMID 41157253, 2025). "Furthermore, the insulin-like growth factor 1 (IGF-1) has been shown to trigger TLR9 expression in glioma cells through activation of hypoxia-induced factor 1 alpha signaling, which in turn stimulates IL-1β, IL-6, IL 8 as well as CXCR4." (PMID 41157253, 2025). "Differential expressions of TLR9 have been observed between normal and tumor cells in various cancers, including head and neck cancer, B-cell chronic lymphocytic leukemia, colorectal cancer, and glioma." (PMID 39123407, 2024). "Several studies have found that increased TLR7 and TLR9 expression in glioma tissues is related to poorer prognosis, while TASL is located downstream of TLR7-9, which indirectly supports the conclusion that high TASL expression is related to poor prognosis of LGG." (PMID 37296415, 2023). "After microglia TLR3 and TLR9 are co-activated, microglia shift to an anti-tumor phenotype and enhance migratory activity to accumulate in glioma tissue, which in turn inhibits glioma cell function by releasing cytokines or directly kills glioma cells by enhancing phagocytic activity of microglia." (PMID 37700840, 2023). "Here, we hypothesized that TLR9 might play dual roles in cancers such as glioma, and we review and summarize the current knowledge about TLR9-signaling in the pathogenesis of glioma." (PMID 36611945, 2022). "Some studies have revealed that TLR9 plays an important role in glioma progression and induction." (PMID 36611945, 2022). "TLR9 activation with CpG ODN promotes glioma stem-like cell (GSC) growth." (PMID 36611945, 2022). "Moreover, another TLR9 agonist, CpGODN107, was investigated as a radiosensitizer in vitro (human glioma U87 cells) and in vivo." (PMID 36611945, 2022). "Furthermore, the activation of TLR9 expressed in glioma cells can effectively promote cellular invasion of cancer cells in vitro." (PMID 36611945, 2022). "In vitro glioma stem cell maintenance was attributed to TLR-9 dependent STAT3 regulation." (PMID 34439380, 2021).
glioma (continued). "In glioma, the expression of TLR9 correlates with malignancy." (PMID 34715891, 2021). "Taken together, these results suggested that HMGB1 could promote the formation of GSCs by primary glioma cells via TLR9 and NEAT1." (PMID 32843056, 2020). "We then tested the effects of these two TLR9 agonists on primary glioma cells." (PMID 32843056, 2020). "Interestingly, in glioma, the TLR9 expression by pDCS is downregulated and both TLR9 and the manipulation of DC activity are proposed to be attractive targets in GBM immunotherapy." (PMID 33066460, 2020). "Therefore, it has been demonstrated that CpG ODN 107 (TLR9 agonist) combined with irradiation (5 Gy) significantly suppresses the growth of glioma cell line in vitro." (PMID 31886298, 2019). "Taken together, CpG ODN107 combined with irradiation could induce autophagic cell death, and this effect was closely related to the TLR9-ERK-mTOR signaling pathway in glioma cells, providing new insights into the investigation mechanism of CpG ODN." (PMID 27251306, 2016). "The presence of HCMV in gliomas may responsible for the high TLR9 expression, however, the relationship between the CMV and TLR9 expression need further investigation." (PMID 20696081, 2010). "Secondly, our findings warrant caution in the directly injection of TLR9 agonist CpG ODN into glioma tissues for the glioma immunotherapy., this conclusion may be contradictory to some researcher's work." (PMID 20696081, 2010). "RT-PCR showed that TLR9 expressed in all the glioma samples and glioma cell lines we examined." (PMID 20696081, 2010). "We demonstrated the relationship between TLR9 expression and glioma progression." (PMID 20696081, 2010). "Our study indicated that the TLR9 signaling pathway constitute an important cellular pathway mediating this interaction in glioma, however, other independent retrospective and prospective studies will be necessary before direct clinical application of the current findings." (PMID 20696081, 2010). "Immunofluorescence was used to determine TLR9 protein expressed in human glioma cell lines." (PMID 20696081, 2010). "In addition, our findings warrant caution in the directly injection of TLR9 agonist CpG ODN into glioma tissues for the glioma immunotherapy." (PMID 20696081, 2010). "The relationship between the expression level of TLR9 and tumor grade of glioma is unknown, to investigate this, large amount of clinical samples are required." (PMID 20696081, 2010). "The upregulation of TLR9 could be beneficial to the tumor, promoting survival and the invasiveness of glioma cells, the selective pressure of the local microenvironment might result in the ultimate higher expression of TLR9." (PMID 20696081, 2010). "However, the exact mechanism for the TLR9 regulation of glioma invasion need further investigation and is out of the focus of this research." (PMID 20696081, 2010). "In addition, combined activation of the endosomal TLR3 and TLR9 in microglia was shown to have synergistic effect both in vitro and in vivo, reinforcing the secretion of proinflammatory factors, phagocytic activity, and suppression of glioma growth." (PMID 34715891, 2021). "We proposed that TLR9 signal pathway may also be important in glioma growth and progression." (PMID 20696081, 2010). "We believe that, just like the TLR9 signal pathways in other cancer cells, the activation of TLR9 may lead to enhanced invasiveness of U87 glioma cells, this was supported by our research, we found that the TLR9 agonist CpG ODN can significantly increased the invasiveness of U87 glioma cells." (PMID 20696081, 2010). "However, in our study, we found the glioma cells do express TLR9." (PMID 20696081, 2010). "Our data indicated that TLR9 may relate to glioma progression and the prognosis of GBM patients." (PMID 20696081, 2010). "Both the sequential TLR9 and TLR3 activation protocol and such engineered DC vaccines present promising novel avenues for the application of DCs in glioma therapy." (PMID 41294838, 2025).
glioma (continued). "When ODN 1826 stimulates TLR9, gliomas undergo caspase-3-dependent apoptosis, extending the lifetime of C57BL/6 mice with an intracranial glioma cell line (GL261)." (PMID 40727443, 2025). "Another recent attempt at PD-1 blockade was demonstrated by Zhu and colleagues, wherein the glioma vaccine called STDENVANT consisted of glioma stem-like cell (GSC) lysate, DCs, and TLR9 agonists, CpG ODNs." (PMID 35745800, 2022). "In glioma, elevated TLR1, TLR2, TLR4, TLR5, TLR6, and TLR9 expressions were observed in tumor cell lines and tissues compared with non-neoplastic brain tissues, particularly in the mesenchymal subtype of GBM." (PMID 34715891, 2021). "We synthesized siRNAs targeting TLR9, and transfected ADV-infected primary glioma cells with these siRNAs." (PMID 32843056, 2020). "Investigation of the molecular mechanisms demonstrated that CpG ODN107 + irradiation increased the levels of TLR9 and p-ERK, and decreased the level of p-mTOR in glioma cells." (PMID 27251306, 2016). "One important line of investigation for the future is to perform in vivo studies of human glioma cell lines in humanized mouse models in order to fully understand the nature of the anti-tumor and pro-tumor effects of TLR4 and TLR9 agonists." (PMID 25411122, 2014). "In glioma cells, IGF-1 induced TLR9 through HIF-1α signaling, mediated by Ras and calmodulin dependent kinase II (CaMK II)." (PMID 25411122, 2014). "To further characterize the possible role of TLR9 expression on tumor cells, we examine the direct effects of CpG ODN upon the proliferation and invasion of glioma cells in vitro." (PMID 20696081, 2010). "Thus we proposed that The TLR9 pathway may also exist and activated in glioma tissues." (PMID 20696081, 2010). "In order to ensure that TLR9 is responsible for the invasion effects induced by CpG ODN, glioma cells were treated with CpG ODN in the presence of chloroquine, which is an inhibitor of endosomal acidification resulting in inhibition of TLR9 signaling." (PMID 20696081, 2010). "Within the family of TLRs, TLR-2, TLR-4, and TLR-9 stand out with unique expression patterns in glioma cell lines, while TLR-7 and 8 remain absent in gliomas." (PMID 39202716, 2024). "Moreover, lncRNA NEAT1 promotes glioma pathogenesis though many of other pathways including NEAT1/miR-449b-5p/c-Met axis, NEAT1/MiR-92b, TLR9/NEAT1/STAT3, NEAT1/microRNA let-7e, miR-152-3p/CCT6A, and miR-139-5p/CDK6." (PMID 33393590, 2021). "Interestingly, prolonged activation of TLR-9 by increasing the concentration of CpG dinucleotide was found to downregulate TLR-9 expression and induce apoptosis of glioma cells, resulting in prolonged survival of mice implanted with GBM cells." (PMID 34439380, 2021). "Our data have shown that in glioma cells, ADV triggers TLR9 to induce GSCs formation." (PMID 32843056, 2020). "Further, TLR9-specific siRNA could affect the expressions of p-ERK and autophagy-related proteins in glioma cells." (PMID 27251306, 2016). "The potential relationship between TLR9 pathway and cell proliferation was explored, we demonstrated that TLR9 activator CpG ODN did not affect the proliferation of glioma cells in vitro." (PMID 20696081, 2010). "Tissue microarry and immunohistochemistry were applied to evaluated TLR9 expression in 292 newly diagnosed glioma and 13 non-neoplastic brain tissues." (PMID 20696081, 2010). "TLR9, mainly as cytoplasmic staining was found to be expressed in gliomas, no strong immunoreactivity (score <4) was detected in non-neoplastic brain tissues." (PMID 20696081, 2010). "Despite these promising results using TLR9 agonists for glioma antitumor therapy, CpG-ODN treatment may not yield beneficial effects in glioma patients showing an increase in tumor size after CpG-ODN intratumoral injection in a rat glioma model." (PMID 36611945, 2022).